HMGB1 (high mobility group box 1)
Diseases named in the same sentence as HMGB1 in open-access papers (continued):
Sharing a sentence is not in itself a finding about the gene and the disease.
cancer (continued). "At present, HMGB1 could be used as a target to regulate the drug resistance and prognostication in cancer." (PMID 37897664, 2024). "In a study investigating oral squamous cell carcinoma (OSCC), it was found that extracellular HMGB1 could be overexpressed as a cancer cell growth factor and upregulate the expression of RANKL in osteoclasts by activating RAGE and TLR4 receptors." (PMID 37897664, 2024). "In cancer, some HMGB1-activated pathways aggravate prognosis by supporting invasion and metastasis." (PMID 38831013, 2024). "HMGB1 releases and pyroptosis induction leads to dendritic cell maturation, educating naïve T cells in lymph nodes, expanding T cells, and developing memory T cells for cancer immunotherapy." (PMID 38566199, 2024). "We also observed a negative relationship between HMGB1 and SCD1, in which additional analysis across cancer sub-types further revealed more dramatic statistical differences between HMGB1 and SCD1 within the “proximal inflammatory” and “terminal respiratory unit” subtypes (not shown)." (PMID 39100092, 2024). "Furthermore, HMGB1 can activate c-Myc signaling, an important pathway that contributes to drug resistance in various types of cancers." (PMID 38725632, 2024). "Reduced HMGB1 promotes cancer cell autophagy, while oxidized HMGB1 promotes cancer cell apoptosis." (PMID 38529373, 2024). "Disrupting the relationship between HMGB1 and Beclin-1/Bcl-2 may be an effective way to regulate autophagy, thus inhibiting the survival of cancer cells." (PMID 37897664, 2024). "Taken together, our results support a model in which HMGB1 binds to different RNA species with differential specificity in human cancer cells, which shall contribute to HMGB1-modulated rRNA modification, protein synthesis function of ribosomes, and differential gene expression including rRNA genes." (PMID 38580917, 2024). "During the occurrence of ICD, cancer cells express or release damage-associated molecular patterns (DAMPs), such as calreticulin (CRT), high mobility group protein 1 (HMGB1) and adenosine 5′-triphosphate (ATP), on the cell membrane or release them extracellularly." (PMID 39949344, 2024). "Therefore, it is important to understand the role of HMGB1 in the cancer diagnosis, prognosis, and treatment." (PMID 38725632, 2024). "Together, these results underscore how different cancer cells respond to the CXCL12/HMGB1 heterocomplex enhancing directional cell migration and invasion, which depends on the balance between maintaining HMGB1 in its reduced form and promptly removing CXCL12 from the microenvironment." (PMID 38803493, 2024). "It has been reported that HMGB1 protein plays a role in cancer progression and response to therapy." (PMID 39100092, 2024). "Additionally, high mobility group box 1 protein (HMGB1), secreted by dying cancer cells through a paracrine mechanism, is involved in radiation-induced PGCCs promoting cancer regeneration via neosis." (PMID 39055650, 2024). "We therefore speculate that HMGB1 may exert some of its biological functions by its RNA binding activities in cancer cells." (PMID 38580917, 2024). "In our study of HMGB1 as a predictive and prognostic biomarker of oncolytic immunotherapy, a concentration of 0.512 ng/mL was determined as the cutoff for categorizing patients into low and high HMGB1 baseline groups in various types of cancer." (PMID 39768997, 2024). "Furthermore, the development of molecular drugs that inhibit the HMGB1/RAGE axis is crucial for cancer therapy." (PMID 38529373, 2024). "After treatment with these drugs, cancer cells release DAMPs, which include HMGB1 from the nucleus, the translocation of CRT from the endoplasmic reticulum to the cell surface, and ATP secreted into the extracellular medium, promoting their recognition by immune cells." (PMID 38992782, 2024). "This review aimed to provide a comprehensive overview of the role of HMGB1 in cancer." (PMID 38725632, 2024).
cancer (continued). "The researches on HMGB1 have mainly focused on cancer cells for now." (PMID 36709284, 2023). "Exposure of OSCC cells to hypoxia was further shown to induce autophagy by activating the signaling pathway of Hypoxia-inducible factor 1-alpha (HIF-1α)/Bcl-2 interacting protein 3 (BNIP3)/Beclin-1 and inducing HMGB1 secretion, thus acting as a survival mechanism for the cancer cells." (PMID 37511951, 2023). "Reversely, a set of DAMP molecules, including HMGB1, may target cancer cells to immunogenic cell death." (PMID 37180096, 2023). "Finally, our study suggests the therapeutic potential of targeting the STAT1/HMGB1/NF-κB signaling axis for the prevention of chronic kidney problems after cisplatin treatment in cancer patients." (PMID 37284446, 2023). "All these findings point out the extreme importance of HMGB1 and RAGE in cancer development and dissemination, especially as many studies show HMGB1 may arise from cancer chemo- and radiotherapy-induced necrotic cell death." (PMID 36982351, 2023). "Targeting HMGB1 might achieve some potential therapeutic effects in cancers via the regulation of ferroptosis." (PMID 36926345, 2023). "Moreover, treatment with liposomal berberine led to CRT exposure on the surface of cancer cells, extracellular ATP, and HMGB1 release." (PMID 38275991, 2023). "In addition to lipid signaling, ferroptotic cancer cells release HMGB1 in an autophagy-dependent manner." (PMID 36861444, 2023). "We included the cancerous cytokine HMGB1 as environmental (cancer) stimulus." (PMID 36993954, 2023). "Furthermore, the high mobility group box 1 (HMGB1) protein is passively released in the extracellular space during cancer cell apoptosis." (PMID 37298262, 2023). "Furthermore, the promotion of inflammation in macrophages by ferroptotic cancer cells released HMGB1 depended on the advanced glycosylation end-product specific receptor (AGER)." (PMID 36926345, 2023). "HMGB1 is known to have diverse functions in both inflammation and the development of cancer." (PMID 37520371, 2023). "Notably, the stimulaotry gene, high mobility group box 1 (HMGB1), was significantly positively associated with CEP55 in all 33 cancers, suggesting involvement in CEP55-related ICP effects." (PMID 37887301, 2023). "Furthermore, HMGB1 has been shown to promote EMT signaling in several cancer types via the RAGE-NF-κB signaling pathway." (PMID 37511951, 2023). "However, the role of cancer-derived HMGB1 in promoting exhaustion through the modulation of immune checkpoint expression has not been investigated." (PMID 36993954, 2023). "DAMPs released during ICD stimulate DC maturation and improve DC functions: adenosine triphosphate (ATP) facilitating DC recruitment and activation, calreticulin (CRT) enhancing cancer antigen engulfment, and high-mobility group box 1 (HMGB1) improving antigen presentation of DCs." (PMID 38008741, 2023). "T lymphocytes promote calreticulin exposure, HMGB1 and IL-1β release, leading to DC uptake and cross presentation, providing a mechanism for amplification and self-perpetuation of the immune response against cancer neoantigens." (PMID 38077402, 2023). "By silencing HMGB1 with shRNA or removing mtDNA from cancer cells, the activation of p38, p65, JNK, and IL-6 expression could be significantly reduced." (PMID 36942262, 2023). "The released HMGB1 promoted cancer cell proliferation and migration in vitro." (PMID 36831371, 2023). "The association of this reduced proteoform of HMGB1 with chemokine activity indicates that cisplatin mediated HMGB1 secretion could activate immune cells during cancer chemotherapy." (PMID 37759736, 2023). "Previous studies indicated that HMGB1 increases PD-L1 expression in cancer cells; however, the modulation of PD-L1-PD-1 by HMGB1 in immune cells remains unknown." (PMID 36993954, 2023). "Furthermore, exosomal HMGB1 promotes cancer cell survival, protects cells from doxorubicin cytotoxicity and increases angiogenesis." (PMID 36982351, 2023).
cancer (continued). "Moreover, F1,6P lowers the affinity of HMGB1 for DNA and DNA adducts, which sensitizes cancer cells to chemotherapeutic drug(s)‐induced DNA replication stress and DNA damage." (PMID 36642839, 2023). "However, cancer cells have also been shown to inhibit the expression of HMGB1, consequently decreasing immune infiltration in several cancers." (PMID 37781042, 2023). "ERK, EMT, and Wnt signaling pathways were activated in cancer cells due to HMGB1 upregulation." (PMID 36709284, 2023). "Cancer cells undergoing ICD contribute to the emission of immuno-stimulatory molecules, such as damage-associated molecular patterns (DAMPs), the most common of which are ATP, high-mobility group box 1 (HMGB1), and calreticulin (CRT)." (PMID 37896190, 2023). "HMGB1 was also found at lower levels in the HPNE control cells than in the cancer cell lines." (PMID 37627239, 2023). "Additionally, two soluble ligands: galectin-9 and high-mobility group protein B1 (HMGB1), produced by dying cancer cells, can also act with TIM-3." (PMID 37444609, 2023). "We conducted an experiment to determine whether exposure to DP increased the secretion of HMGB1 in A549 or K562 cells and thereby increased the cancer cell-killing activity of NK cells." (PMID 37108220, 2023). "The areas under the curve (AUCs) of the ROC curves for differentiation of cancer vs. healthy were 0.77 for HMGB1, 0.65 for sRAGE and 0.78 for the HMGB1/sRAGE ratio, and slightly lower for the differentiation of cancer vs. benigns with 0.72 for HMGB1, 0.61 for sRAGE and 0.74 for the ratio of both." (PMID 37894448, 2023). "Cancer‐cell‐secreted CXCL11 could promote CD8 T cell infiltration through the docetaxel‐induced release of HMGB1 in NSCLC." (PMID 36822595, 2023). "On the other hand, HMGB1 plays paradoxical roles in cancer, depending on its localization." (PMID 37251376, 2023). "Cancer cells undergoing immunogenic cell death are characterized with the release of danger associated molecular patterns (DAMPs), such as calreticulin (CRT), adenosine triphosphate (ATP) and high mobility group box 1 (HMGB1), etc.." (PMID 36927803, 2023). "ML266-induced cancer cell ferroptosis can release ATP and HMGB1, as well as expose CRT." (PMID 38288118, 2023). "HMGB1 is often considered as a cancer therapeutic target but with many challenges." (PMID 36642839, 2023). "Interestingly, for cancer cells, we found for the first time that HMGB1-mediated CTSL and autophagy-lysosome pathway by RNA-seq is strongly linked to the effects of naphplatin-mediated antitumor and anti-metastasis effects." (PMID 37537587, 2023). "Reduced nuclear HMGB1 may therefore leave the genome vulnerable to DNA damage at this critical stage of cancer development." (PMID 36980751, 2023). "Genetic alterations of HMGB1 were observed among different cancer samples from the TCGA database." (PMID 35765707, 2022). "Therefore, the HMGB1 expression has been reported in various diseases, such as malignant tumors, sepsis, and arthritis." (PMID 35328426, 2022). "In particular, it would be interesting to determine whether HMGB1-ΔC-TM might help combining cancer cell directed and immune therapies." (PMID 35887213, 2022). "However, Vanguard downregulation under glucose limiting conditions promotes HMGB1 translocation from the nucleus, increasing DNA damage, and compromising cancer cell growth and viability." (PMID 36047643, 2022). "Increased chemotactic response toward the presence of HMGB1 was observed in B cells, suggesting that cancer-derived HMGB1 could be an important factor favoring B-cell retention within the TME." (PMID 34617194, 2022). "Ferroptotic cancer cells can release HMGB1 and promote macrophage inflammatory response." (PMID 35444656, 2022). "Moreover, the level of extracellular HMGB1 has also been proven to correlate with the differentiation of various cell types, such as T cells, stem cells and cancer cells." (PMID 35637945, 2022).
cancer (continued). "Our results demonstrate that HMGB1-ΔC is consistently more active on cancer cells than its full-length counterpart, suggesting that the acidic tail might negatively modulate HMGB1 cytotoxic activity." (PMID 35887213, 2022). "Moreover, it was shown that inhibited miR-34a led to the down-regulation of NF-κB, promoting the expression of HMGB1 and potentially contributing to portal vein tumor thrombus and cancer metastasis." (PMID 36142450, 2022). "In the initial sections of this review, we described the role of RAGE ligands in cancer progression, particularly AGEs, HMGB1, S100 proteins, adhesion molecules, complement components, ALEs, and lipopolysaccharides, which play important roles in cancer biology in conjunction with RAGE." (PMID 36613714, 2022). "Cancer cells with a high expression of HMGB1 may induce cancer cell invasion, migration, and metastasis, and a proliferation of endothelial cells in vitro and neovascularization in vivo." (PMID 36142391, 2022). "However, PKM2 expression levels cannot be used as a unique biomarker to predict cancer cell response towards HMGB1 derivatives." (PMID 35887213, 2022). "The results of this study show that C6, which was discovered as a papaverine 3D pharmacophore mimetic compound, has both potent anti-inflammatory and anti-cancer activities by the suppression of the HMGB1-RAGE-ERK1/2 signaling pathway, inducing apoptosis to cancer cells." (PMID 35408786, 2022). "Studies have revealed that high mobility group box-1 (HMGB-1) in virus therapy with oncolytic adenoviruses as well as human inhibitory receptors Ig-like transcript 2 (ILT2) in the treatment of cancer with vaccinia virus can be used as predictive, prognostic, and treatment monitoring biomarkers." (PMID 35295845, 2022). "Finally, this study comprehensively evaluates the genetic variation of HMGB1 in human malignant tumours." (PMID 35765707, 2022). "Of note, neutrophilic HMGB1 integrated with NETs is involved in EMT induction in cancer cells." (PMID 36555469, 2022). "HMGB1 can affect the efficacy of radiotherapy and has an impact on the survival of cancer patients." (PMID 35812184, 2022). "These receptors could be activated by another representative DAMP ligand, high mobility group box 1 (HMGB1), leading to metastasis in several sorts of cancer cells." (PMID 36142212, 2022). "However, HMGB-1 release from MC38 cells in general was reported to be relatively low compared to other cancer cell lines." (PMID 35658868, 2022). "Moreover, exploiting Vanguard to target HMGB1 appears to circumvent concerns of the potential dual roles of HMGB1 in cancer." (PMID 36047643, 2022). "HMGB1-induced autophagy can also be regulated by several miRNAs, a family of small non-coding RNAs which, through epigenetic mechanisms, play an important role in the maintenance of immune homeostasis, cancer progression, and inflammation." (PMID 36012593, 2022). "As DAMPs, modulating HMGB1 activity in inflammation, immune response and tissue repair could generate invaluable treatment strategies for various diseases, including cancer." (PMID 36158661, 2022). "Furthermore, HMGB1 is closely related to cancer immunity microenvironment, and exosome-derived HMGB1 can promote the expansion of TIM-1+ Regulatory B cells through TIL2/4 and MAPK signaling pathways, resulting in immune escape in HCC." (PMID 36267972, 2022). "Based on these data, we designed a study aimed at identifying the role of cancer-derived HMGB1 in the immune contexture of the TME, with particular focus on B cells, which could potentiate the tumorigenicity of ESCC through angiogenesis." (PMID 34617194, 2022). "Interestingly, the activity of the active form of PKM2 can efficiently be inhibited by the high-mobility group box 1 (HMGB1) protein, leading to a rapid blockage of glucose-dependent aerobic respiration and cancer cell death." (PMID 35887213, 2022).
cancer (continued). "HMGB1 plays a complex role in a variety of biological processes and has a variety of functions in maintaining cell homeostasis, and it is involved in the development of many diseases, such as inflammation and cancer." (PMID 35273678, 2022). "Therefore, potential confounders must be considered when monitoring and interpreting HMGB1 levels during cancer treatment." (PMID 34671818, 2022). "HMGB1 transmits danger signals by binding with various receptors, thus intensifying a series of cellular reactions that are closely related to inflammatory diseases, autoimmune diseases, and cancer." (PMID 35911735, 2022). "We found that HMGB1 may function in the regulation of cancer through cell cycle and DNA signaling pathway-related functions by GO/KEGG enrichment analysis." (PMID 36230798, 2022). "HMGB1 is a conserved evolutionarily DNA-binding nuclear protein that has been represented as a damage-associated molecular pattern (DAMP) protein involved in several disease states, including sepsis, arthritis, and cancer." (PMID 34617194, 2022). "However, besides being involved in ICD in cancer, HMGB1 also mediates diverse responses to inflammatory and infectious diseases such as, for example, pancreatitis and sepsis, pneumonia, stroke, or vasculitis." (PMID 34671818, 2022). "The HMGB1 released by ferroptotic cancer cells activated innate immune cells and triggered an inflammatory response that was dependent on HMGB1 binding to the cognate receptor, advanced glycosylation end product-specific receptor (AGER), and not toll-like receptor 4 (TLR4) on macrophages." (PMID 35065965, 2022). "Furthermore, ECT and nsPEF have also been shown to release several DAMPs including ATP, HMGB1, and calreticulin in different cancer models." (PMID 35372046, 2022). "High mobility group box 1 (HMGB1) protein can block aerobic respiration in cancer cells." (PMID 35477503, 2022). "Additionally, we explored the association between HMGB1 gene mutation and TMB or MSI in considering a quantifiable biomarker based on gene mutations in various types of cancer, in which we examined several tumors in the TCGA dataset." (PMID 36230798, 2022). "The patterns of genetic alterations for HMGB1 differ across cancer types." (PMID 35765707, 2022). "Furthermore, other moieties, such as high mobility group box protein 1 (HMGB1), which induce TNFα expression in cardiac myocytes were also increased in cancer cachexia models." (PMID 35326491, 2022). "This consideration might be important when monitoring ICD by HMGB1 during cancer therapy if inflammation and/or infection accompany the treatment." (PMID 34671818, 2022). "Pyroptosis-like immunogenic cell death (ICD) leads to the severe release of immunoregulatory molecules of IL-1β, IL-18, HMGB1, and ATP, and pyroptotic cancer cells were uptaken by antigen-presenting cells which suggested that pyroptosis were closely correlated to immune activity." (PMID 36281290, 2022). "In addition to cancer cells, bone marrow-derived macrophages also promote HMGB1 release via secretory autophagy." (PMID 35927755, 2022). "This may contribute to a better understanding of virus-host interaction during HBV infection, and to the development of HBV infection epigenetic drugs and re-consideration of cancer therapeutics strategies, where HMGB1 is used as an anti-cancer target." (PMID 35679251, 2022). "HMGB1 inhibitors, such as gefitinib, and RAGE inhibitors might play an essential role in preventing cancer regrowth, as suggested by HMGB1-related autophagy in chemotherapy." (PMID 36613714, 2022). "Therefore, the HMGB1 release pattern and its effects should be studied in various types of cancers using in vitro and in vivo models." (PMID 35336794, 2022). "However, unlike NK cells, cytotoxic CD8+ t cells require priming by danger indicants/alarmins, such as HMGB1, ATP or hsp70 to detect and eliminate cancer cells." (PMID 36613754, 2022).